FGR (FGR proto-oncogene, Src family tyrosine kinase)
Diseases named in the same sentence as FGR in open-access papers:
FGR is named in the same sentence as 43 diseases in open-access papers, as found by Europe PMC text mining. Sharing a sentence is not in itself a finding about the gene and the disease. The quoted sentences say what the papers report.
breast carcinoma (3 papers, 2016 to 2019). "FGR and ZAP70 have diagnostic and therapeutic potential due to their relationship with breast cancer development and progression." (PMID 27911271, 2017). "There is limited data on co-expression of FGFR/FGR amplifications and PI3K/ AKT/mTOR alterations in breast cancer." (PMID 27489863, 2016). "Among ER+ breast cancers, 15% harbored FGFR1 gene amplification and/or mRNA overexpression whereas 2.5, 1.9, 2.4, and 1.7% harbored amplification and/or mRNA overexpression of CRKL, HCK, FRK, and FGR, respectively." (PMID 30914635, 2019).
colorectal cancer (3 papers, 2015 to 2025). A primary or metastatic malignant neoplasm that affects the colon or rectum. "FGR encodes a Src family tyrosine kinase and has been reported to have association with the tumor progression as a proto-oncogene in some cancers such as colorectal cancer." (PMID 35675043, 2022).
ovarian carcinoma (3 papers, 2020 to 2025). A malignant neoplasm originating from the surface ovarian epithelium. "Previous studies have highlighted FGR’s potential role in the progression of ovarian carcinoma and its emerging clinical relevance in CRC." (PMID 39788945, 2025). "Because FGR/FGFR signaling is a well-established signaling pathway that leads to uncontrollable cell growth, we next assessed the cytotoxic and antiproliferative effects of AZD4547 in various ovarian cancer cell lines." (PMID 34639155, 2021).
Arthritis (2 papers, 2023 to 2025). Inflammation of a joint. "Later, they demonstrated that HCK, FGR, LYN are critical in generation of in vivo inflammatory environment in autoantibody-induced arthritis and other inflammation mouse models." (PMID 37463911, 2023). "Additionally, many of the other proteins have been indicated in arthritis or pain conditions such as VEGFR3, FGR, TNFRSF6B, FGF19, DKK3 and proteins belonging to CCL, MMP and CXCL families." (PMID 41170664, 2025).
Hypertension (2 papers, 2022 to 2025). The presence of chronic increased pressure in the systemic arterial system. "Our group recently highlighted FGR and hypertension in the offspring from the perspectives of mechanistic linkage and therapeutic directions." (PMID 35354941, 2022).
periodontitis (2 papers, 2022 to 2024). An acute or chronic inflammatory process that affects the tissues that surround and support the teeth. "Except for FGR, all other genes exhibited significant upregulation in the periodontitis group." (PMID 38491529, 2024). "An online differential expression analysis conducted using OralExplorer revealed several genes that were significantly upregulated in all six periodontitis-related datasets, including IL-1β, SRGN, CXCR1, FGR, ARHGEF2, and PTAFR." (PMID 38491529, 2024). "The analysis revealed simultaneous significant upregulation of IL1β, SRGN, CXCR1, FGR, ARHGEF2, and PTAFR in all six periodontitis-related datasets." (PMID 38491529, 2024).
acute myeloid leukemia (1 paper, 2020). Acute myeloid leukemia (AML) is a group of neoplasms arising from precursor cells committed to the myeloid cell-line differentiation. "Previous studies had suggested that expression of FGR and HCK in acute myeloid leukemia blasts was associated with early commitment and differentiation events in the monocytic and granulocytic lineages." (PMID 32708273, 2020).
age-related macular degeneration (1 paper, 2018). Age-related loss of vision in the central portion of the retina (macula), secondary to retinal degeneration. "Another study reported that FGR (ENSP00000363115) may also participate in eye diseases, including age-related macular degeneration and uveitis." (PMID 30349554, 2018).
autoimmune disease (1 paper, 2011). A disorder resulting from loss of function or tissue destruction of an organ or multiple organs, arising from humoral or cellular immune responses of the individual to their own tissue constituents. "However, it is interesting to note that they contain genes associated with disease in humans and dogs including epilepsy (KCNQ5), cancer (NPM1, FGR), and autoimmune disease (IL6)." (PMID 22022279, 2011).
B cell lymphoma (1 paper, 2016). "In silico analysis of B cell lymphoma samples (n = 1200) showed a wide range of FGR expression indicating that FGR expression might help to stratify patients; however, clinical data were not available, nor results from treatment with HDAC inhibition." (PMID 27766120, 2016).
leukemia (1 paper, 2025). A malignant (clonal) hematologic disorder, involving hematopoietic stem cells and characterized by the presence of primitive or atypical myeloid or lymphoid cells in the bone marrow and the blood. "The present studies show that FGR causes the signaling and phenotypic shift characteristic of RA in human myeloid progenitor leukemia cells." (PMID 40116400, 2025). "FGR targets several key proteins to promote leukemia cell differentiation." (PMID 40116400, 2025).
lung carcinoma (1 paper, 2013). "Co-activation of MET, AXL, ERBB2, and EPHA2, and co-activation of DDR1 with EGFR, DDR2, HCK, PDGFRA, and FGR is evidence that simultaneous activation of multiple tyrosine kinases may be common in lung cancer." (PMID 23300999, 2013).
nasopharyngeal carcinoma (1 paper, 2025). A carcinoma arising from the nasopharyngeal epithelium. "Indeed, increased FGR has been associated with active immune signaling in nasopharyngeal carcinoma and represents a strong candidate for modulating the efficacy of immunotherapy." (PMID 41225774, 2025).
Obesity (1 paper, 2013). Accumulation of substantial excess body fat. "Thus, the anti-obesity effects of fGR were not from the inhibition of food consumption." (PMID 24177708, 2013).
preeclampsia (1 paper, 2023). Preeclampsia is a hypertensive disorder of pregnancy that is characterized by new-onset hypertension with proteinuria presenting after 20 weeks of gestation, and depending on mild or severe forms may initially present with severe headache, visual disturbances, and hyperreflexia. "MKNK1 was found significantly increased in FGR-affected placenta, while its function in preeclampsia remained to be investigated." (PMID 37020283, 2023).
uremia (1 paper, 2023). A clinical syndrome associated with the retention of renal waste products or uremic toxins in the blood. "Our study systematically identified three candidate hub genes (FGR, LCP1, and C5AR1) and established a nomogram to assist in the diagnosis of USCP with uremia using various bioinformatic analyses and machine learning algorithms." (PMID 36823662, 2023). "The current study systematically identified three candidate hub genes (FGR, LCP1, and C5AR1) and established a nomogram to assist in diagnosing USCP with uremia using various bioinformatic analyses and machine learning algorithms." (PMID 36823662, 2023).
vasculitis (1 paper, 2026). "In Family C, we describe a large pedigree carrying a novel missense variant in FGR (p.Y523H), establishing FGR as a new cause of monogenic vasculitis." (PMID 41920357, 2026).
cancer (15 papers, 2009 to 2025). A tumor composed of atypical neoplastic, often pleomorphic cells that invade other tissues. "FGR encodes Src family tyrosine kinases and functions as a proto-oncogene in cancer development." (PMID 40860289, 2025). "A previous study showed that the FGR/FGFR pathway plays an important role in the migration of cancer cells." (PMID 34639155, 2021). "Of all of the other family members (FYN, YES, BLK, YRK, FGR, HCK, LCK, and LYN) cSrc is the most often associated with cancer progression." (PMID 33841333, 2021). "The finding that FGR’s influence on DKK1 is mediated through a signaling pathway involving SP1 highlights the intricate regulatory processes that dictate cancer cell behavior and identifies the FGR-PI3K-AKT-SP1 pathway as a valuable target for therapeutic intervention." (PMID 39788945, 2025). "Furthermore, rare N-terminal fusions of FGR kinases have been reported during cancers supporting to directly evaluate the effects of these fusions by our approach." (PMID 36423812, 2022). "Genes PRKCZ (Protein Kinase C Zeta), FGR (Src family protein), KDM4B, MPO, COL11A1, FUT4 (Fucosyltransferase IV), and APEH (acylpeptide hydrolase) are directly associated with tumor aggressiveness, growth, and migration, and invasiveness, resulting in poor clinical outcome in cancer patients." (PMID 38086861, 2023). "Even though FGR has not been genetically linked to cancer to date, it has been hypothesized that its expression could compensate for SRC inhibition." (PMID 25204415, 2014). "Therefore by using approved non-small lung carcinoma drug Crizotinib, it may be possible to target SRC or FGR and therefore find its new uses in different cancer types." (PMID 25324859, 2014). "Several proteins involved in carcinogenesis or leukemogenesis are increased for clinical responders (ANO6, CHI3L1, CTSG, ELANE and FGR), suggesting that the sensitivity to ATRA/VP additionally depends on more general functions involved in cancer development." (PMID 33946813, 2021). "With regard to up-regulated DEGs enriched in immune response, it is now well-established that FGR, CXCL1, NLRC4 and S100A9 influence the pathogenesis of cancer by modulating immune responses and promoting progression, aggressiveness and cell survival 32-35." (PMID 32922167, 2020). "Activated membrane SFKs member, FGR and HCK can work in parallel to promote cancer development and weaken lymphocytic infiltration." (PMID 33162805, 2020). "It included a number of genes with obvious cancer relevance including CD44, catenin b1 (CTNNB1), vimentin (VIM), cathepsins B and S (CTSB, CTSS), MMP9, XIAP, JunD, numerous proto-oncogenes (REL, YES, SET, FGR, CRK), and HSP90AA1 (which is a chaperone which stabilizes MIF as a client)." (PMID 28957348, 2017).
tumor (14 papers, 2014 to 2025). "The present results indicate that FGR can also do essentially the opposite; that is, propel differentiation and loss of the tumor phenotype." (PMID 40116400, 2025). "Knockdown of FGR in CT-26 and MC-38 subcutaneous tumor models resulted in reduced tumor volumes, although these FGR-deficient groups showed less responsiveness to DCC-2036." (PMID 39788945, 2025). "Additionally, FGR knockdown using shFGR lentiviruses in CT-26 and MC-38 subcutaneous tumor models led to reduced tumor volumes, although FGR-deficient groups showed lessened sensitivity to DCC-2036." (PMID 39788945, 2025). "Using shFGR lentiviruses, we achieved FGR knockdown in CT-26 and MC-38 homograft mouse models, leading to significant tumor reduction." (PMID 39788945, 2025). "The promising aspects of DCC-2036 necessitate further exploration of its direct anti-tumor activities and its role within the FGR signaling pathway." (PMID 39788945, 2025). "In the TCGA LIHC and GTEx datasets, SRC and YES1 were also significantly upregulated in tumor tissues relative to normal liver tissues (p < 0.01 for both), while FGR and FYN remained unchanged." (PMID 40650282, 2025). "Our network analysis also identified key bridging roles for AIF1 and FGR, suggesting potential points of interaction between stromal and immune components of the tumor microenvironment." (PMID 41225774, 2025). "The anti-tumor effects of DCC-2036 on CRC are mediated by its capacity to activate anti-tumor T-cell immunity via the FGR/AKT/SP1/DKK1 axis." (PMID 39788945, 2025). "Accordingly, and in line with the literature, strong correlation was found between the relative immune fraction and the levels of FGR and the SRC-B sub-family (except LYN), suggesting their expression to be associated with the tumor immune microenvironment." (PMID 39390250, 2024). "In all three cases, FGR mRNA expression in the samples harbouring a fusion was among the highest compared with all other tumours of that tissue type." (PMID 25204415, 2014). "Here, we show for the first time that genetic events can lead to FGR overexpression in primary tumour samples." (PMID 25204415, 2014). "Nevertheless, there is a paradox regarding what determines whether FGR has pro-tumor or anti-tumor effects in different contexts." (PMID 40116400, 2025). "Given the role of many SFKs in immune signaling pathways, increased phosphorylation of SFKs, such as LCK, LYN, FYN, and FGR could be associated with immune cell activation, rather than tumor cell signaling." (PMID 36077757, 2022). "In the MC-38 tumor-bearing mouse model, FGR overexpression negated the suppressive impact of atezolizumab, supporting the notion that CD8+ T cell deficits within the tumor milieu limit immunotherapeutic outcomes in CRC." (PMID 39788945, 2025). "The silencing of FGR markedly boosted CD8+ T cell infiltration and activation, significantly curtailing tumor growth in vivo." (PMID 39788945, 2025). "Immunohistochemical assessments of CT-26 tumor models treated with DCC-2036 confirmed the suppression of p-FGR, emphasizing FGR’s critical role in the drug’s action mechanism." (PMID 39788945, 2025). "Lastly, in CR-TNBC patient P942, the baseline PDX tumor (BTY14) had high phosphorylation on the shared pTyr sites of SRC, FYN, LCK, YES1, and FGR as well as SFK substrates such as tensin, SHIP-1 (INPP5D), AFAP1L2, paxillin, and PTK2." (PMID 36077757, 2022). "Consequently, targeting the FGR-AKT-SP1-DKK1 pathway with DCC-2036 could potentiate immunotherapy by enhancing CD8+ T cell functionality and their tumor infiltration." (PMID 39788945, 2025). "In keeping with the non-redundant role of the FGF/FGR system in primary cilium length determination, NSC12 induces the elongation of primary cilium in FGF-dependent tumor cells, thus acting as a ciliogenic anticancer molecule in vitro and in vivo." (PMID 32630309, 2020).
kidney (1 paper, 2022). "Many of these genes have been shown to be associated with steady-state, heat tolerance and renal function; for example, EXOC3 maintains organ homeostasis by driving lipid metabolism, FGR causes kidney injury, GPR3 is a receptor gene involved in adipose thermogenesis and MLX regulates metabolism." (PMID 36552284, 2022).
FGR also shares sentences with these, for which no sentence is quoted: melanoma (3 papers); atherosclerosis (2); Alzheimer disease (1); chronic lymphocytic leukemia (1); colon cancer (1); COVID-19 (1); cystadenocarcinoma (1); diffuse large B-cell lymphoma (1); endothelial dysfunction (1); epilepsy (1); follicular lymphoma (1); hairy cell leukemia (1); hearing loss (1); Hepatic steatosis (1); hypothyroidism (1); infection (1); Insulin resistance (1); leprosy (1); ovarian serous cystadenocarcinoma (1); pulmonary veno-occlusive disease (1); Sepsis (1); skin cutaneous melanoma (1); uveitis (1).